IL1B (interleukin 1 beta)
Diseases named in the same sentence as IL1B in open-access papers (continued):
Sharing a sentence is not in itself a finding about the gene and the disease.
autism (continued). "Previous studies have shown that high levels of IL-6, TNF-α, and IL-1β are correlated with the severity of autism symptoms, which include stereotypical behaviors and impaired communication skills." (PMID 36268027, 2022). "In this review, we found elevated levels of IL-6, TNF-α, and IL-1β in the plasma/serum of individuals with autism." (PMID 36268027, 2022). "As for autism, many studies indicated that levels of brain cytokines, including IL-6 and IL-1β, were significantly higher in autistic children compared with TD controls." (PMID 36082034, 2022). "For example, several studies have identified a correlation between abnormal levels of several cytokines in neonatal bloodspots, such as IL-1β, IL-6, IL-8, and RANTES, and increased risk of developing autism." (PMID 36268027, 2022). "In this review, we found that IL-6, IL-17, TNF-α, and IL-1β were increased in the in the serum but unchanged in the plasma in subjects with autism." (PMID 36268027, 2022). "In comparison to controls displaying developmental disabilities other than autism, plasma levels of cytokines IL-1β, IL-6, IL-8 and IL-12p40 were increased in children with ASD, which correlated with the severity of the disease." (PMID 34589798, 2021). "Five already reported autism associated pro-inflammatory cytokines [interferon-γ (IFN-γ), interleukin-1β (IL-1β), IL-6, IL-12, and tumor necrosis factor-α (TNF-α)] were detected in plasma by enzyme-linked immunosorbent assay (ELISA) analysis." (PMID 30941018, 2019). "Reduced levels of IL-1β (p < 0.001), IL-8 (p < 0.001), MIP-1β (p = 0.006), PDGF-BB (p = 0.005), and VEGF (p = 0.03) were associated with increased severity of autism in females." (PMID 29214007, 2017). "Previous reports on autism include findings regarding changes in IL-1β, IL-10, IL-6, IL-17, and IL-12 cytokines and differential cellular immune response associated with disease severity and impairment in behaviors in ASD." (PMID 27983615, 2016). "Significant differences were found to IL-1β, IL-6, IL-17, IL-12p40, and IL-12p70 cytokines in individuals with autism compared with AMTD (p < 0.05)." (PMID 27983615, 2016). "Together with our data on impaired communication and socialization, repetitive/restricted behaviors, and increased serum IL-1β levels, we concluded that our model of LPS exposure in prenatal rats on GD 9.5 is a robust rat model of autism." (PMID 26218250, 2015). "The increased serum IL-1β levels in adult offspring prenatally exposed to LPS corroborate with our model of prenatal LPS exposure is an experimental autism model." (PMID 24312647, 2013). "Food refusal, characteristics of autism, limited variety, and tactile sensitivity served as dependent variables in relation to IL-1β, IL-6, age, and gender." (PMID 40002751, 2025). "We demonstrated a difference in effect between genders on cytokines on IL‐1β levels in autism." (PMID 39401991, 2025). "However, IL1B exhibited a mild, but insignificant increase in these cell lines in autism vs. control subjects." (PMID 38994948, 2024). "They demonstrated that the proinflammatory cytokines IL-12, IL-6, IL-1β and INFγ were significantly increased in patients with severe forms of autism, while the increase in the anti-inflammatory IL-10 was a protective factor against autism." (PMID 36835652, 2023). "However, in vitro, Jyonouchi and his group observed that stimulated peripheral blood mononuclear cells (PBMCs) from children with autism secrete significantly higher amounts of soluble IL-1β compared with normal controls." (PMID 25729218, 2015). "Indeed, it has been demonstrated that macrophages are altered in autism and this pathology is accompanied by an activation of the macrophages, together with immune alterations and pro-inflammatory cytokines (that is IL-1β) over-production." (PMID 24739187, 2014).
autism (continued). "Involvement of IL-1β in the physiopathology of autism is generally supported by several studies reporting higher levels of this cytokine in the plasma of children with ASD, high-functioning children with ASD, and adults with severe ASD compared with unrelated controls." (PMID 23497090, 2013). "In addition to the previous findings of autistic-like behaviors, including impairments in communication and socialization and induction of repetitive/restricted behavior in male, but not female, rats, higher levels of IL-1β are also associated with autism." (PMID 24312647, 2013). "Background/Objectives: Elevated cytokine levels, including IL-6 and IL-1β, can contribute to persistent brain inflammation in children with autism and cytomegalovirus (CMV) infection, exacerbating autism-related behaviours and symptoms." (PMID 40002751, 2025). "We found that compared with controls, in subjects with autism, cytokines IL-6, IL-17, TNF-α, and IL-1β increased in the plasma and serum." (PMID 36268027, 2022). "Collectively, we found increased levels of IL-6, IL-17, TNF-α, IL-1β, IFN-γ, RANTES, and IL-8 in the plasma/serum in autism, which is overall consistent with the findings from previous systematic reviews." (PMID 36268027, 2022). "Altogether, we suggest that monocytes are the predominant cells contributing to the elevated cytokine levels of IL-6, TNF-α, and IL-1β in autism, along with CD4+ T cells, which act as another source of IL-1β, whereas neutrophils are another source of IL-6." (PMID 36268027, 2022). "Increased concentrations of proinflammatory cytokines, including IL-1β and IFN-γ, in children diagnosed with autism may result in persistent brain inflammation, which can impact neurological development and behaviour." (PMID 40002751, 2025). "Several studies also indicate that increased levels of IL-6 and IL-1β induced by CMV infection may impact the nervous system, particularly in patients with neurological disorders such as autism or other neurodegenerative diseases." (PMID 40002751, 2025). "In addition, IL-1β levels are markedly increased in post-stimulated monocytes and CD4+ T cells in autism." (PMID 36268027, 2022). "Furthermore, stereotypic behavior, a core symptom of autism, seemed to correlate with down-regulation of TGF-β1 and GM-CSF, as well as up-regulation of IL-1β, IL-6, IL-8, IL12p40, TNF-α, and interferon (IFN)-γ." (PMID 35328471, 2022). "Our results showed that maternal diabetes-mediated autism-like offspring had significant GI symptoms, together with suppressed RORA expression in PBMC and increased secretion of proinflammatory cytokines, including IL1β, IL6, MCP1 and IL17A." (PMID 35164690, 2022). "We chose to measure IL-1β because we recently reported that the neuropeptide neurotensin (NT) stimulates human microglia to secrete IL-1β, which has been shown to be increased in the brains of children with ASD, and in a mouse model of autism." (PMID 30149804, 2018). "Interestingly, the increase in IL-6, IL-17, TNF-α, and IL-1β in the serum was in accordance with the elevated levels of these cytokines in in vitro stimulated neutrophils, monocytes, and CD4+ T cells in individuals with autism, as compared with controls." (PMID 36268027, 2022). "The expression of IL-1β, IL-6, IL-17, and TNF inflammatory molecules is increased in the brain, cerebrospinal fluid, and serum of some patients with ASD, whereas NF-kB is activated in the brain, which then stimulates peripheral blood immune cells in patients with autism." (PMID 28808521, 2017). "In contrast, the persistent inflammatory condition in autism may inhibit IL-38 expression via negative feedback processes involving pro-inflammatory cytokines such as TNF-α and IL-1β." (PMID 41425587, 2025). "Additionally, the levels of IL-6 and IL-17, but not TNF-α and IL-1β, were consistently higher in the unstimulated neutrophils, monocytes, and CD4+ T cells in autism subjects, as opposed to the controls." (PMID 36268027, 2022).
status epilepticus (40 papers, 2011 to 2025). Status epilepticus is defined as a continuous seizure lasting more than 30 min, or two or more seizures without full recovery of consciousness between any of them. "One particular proinflammatory cytokine, interleukin-1 beta (IL-1β) has been implicated in experimental models of status epilepticus." (PMID 36970506, 2023). "In a study, BDNF and FGF-2 induced a rapid attenuation of astrocytosis and microgliosis and prevented the IL-1β overexpression that is typical of the post-status epilepticus period." (PMID 38673746, 2024). "In animal models of kainic acid (KA)-induced status epilepticus (SE), inflammatory cytokines like interleukin-1 beta (IL-1β), interleukin-6 (IL-6), and tumor necrosis factor alpha (TNF-α) were notably increased in microglia following seizures." (PMID 39684432, 2024). "Specifically, the delivery of FGF-2 and BDNF in the rat hippocampus after pilocarpine-induced status epilepticus reduced various markers of inflammation including astrocytosis, microgliosis, and IL-1β expression." (PMID 38673746, 2024). "In particular, the level of IL-1β expression in mice brains with status epilepticus was higher than that in control mice." (PMID 35837232, 2022). "IL-1β is strongly induced in activated microglia and astrocytes during the acute phase of status epilepticus and in the chronic phase of spontaneous seizures in brain areas involved in seizure generation and propagation and is mainly sustained by astrocytes." (PMID 35837232, 2022). "CCR2 is related to the regulation of other pro-inflammatory mediators and was shown to be required for production of IL-1β after convulsant-induced status epilepticus." (PMID 34512245, 2021). "The expression levels of microglial pro-inflammatory cytokines (TNF-α and IL-1β) and anti-pro-inflammator cytokines (IL-10 and IL-4) increase in brain after status epilepticus." (PMID 34924959, 2021). "There is evidence that the initial episode, i.e., status epilepticus, can be induced by pilocarpine through a primary peripheral effect on white blood cells, leading to increased serum levels of IL-1β, which alters BBB permeability." (PMID 31040818, 2019). "For instance, blocking of the IL-1β signaling is reported to prevent status epilepticus in epileptic patients." (PMID 31208341, 2019). "As an index of neuroinflammation, we measured Il1b and Tnfa mRNA levels by RT-qPCR in the mouse hippocampus from 2 h until 7 days post-status epilepticus to encompass the epileptogenesis phase preceding the onset of spontaneous seizures." (PMID 30307467, 2018). "Administration of PD1n-3 DPA-ME (20 or 200 ng/μl) significantly reduced in a dose-dependent manner hippocampal Il1b and Tnfa mRNAs expression after status epilepticus when compared to mice administered vehicle only." (PMID 30307467, 2018). "Following an insult, such as a seizure or period of status epilepticus, pro-inflammatory cytokines, such as IL-1β, tumor necrosis factor-α (TNF-α) and IL-6 are released in the brain, primarily from astrocytes and microglia." (PMID 29563872, 2018). "In another study, peak pro-inflammatory cytokine effects occurred 6 h after status epilepticus, whereas the peak effect of the anti-inflammatory cytokine IL-1Ra was delayed and occurred 24 h after IL-1β." (PMID 29017522, 2017). "We counted the number of highly IL-1β immunoreactive cells and measured the fluorescence intensity derived from acute status epilepticus." (PMID 28446773, 2017). "Consistent with reduced P2X7R function, contralateral levels of IL-1β were lower relative to the ipsilateral hippocampus after status epilepticus." (PMID 26631939, 2015). "Ant22-mediated increases in contralateral hippocampal levels of c-Fos, Arc and IL-1β expression were all blocked in P2rx7−/− mice subjected to status epilepticus confirming the pro-excitability and pro-inflammatory effects of Ant22 were mediated by the P2X7R." (PMID 26631939, 2015).
status epilepticus (continued). "Inflammation markers IL-1β and Tnfα were also significantly elevated at 72 h after status epilepticus in the contralateral hippocampus of Ant22 mice compared to Scr mice." (PMID 26631939, 2015). "In contrast, levels of IL-1β (transcript and protein) and Tnfα were elevated at this time point after status epilepticus in the contralateral hippocampus of Ant22-treated mice." (PMID 26631939, 2015). "We investigated Kir4.1 (Kcnj10) and IL-1β mRNA expression in the temporal cortex in a rat model of temporal lobe epilepsy 24 h and 1 week after induction of status epilepticus (SE), using real-time PCR and western blot analysis." (PMID 23270518, 2012). "Our patients with intractable epilepsy experiencing status epilepticus attacks also showed high IL-1β, IL-6 and HMGB1 levels." (PMID 21989210, 2011). "Furthermore, we observed that, when exposing the animals to more Il1b by silencing its endogenous antagonist Il1rn, there was a better response to status epilepticus with decreased animal mortality in the acute phase of the PILO model." (PMID 35061107, 2023). "Overexpression of GPR120 significantly alleviated epileptic activity, reduced neuronal death after status epilepticus (SE), downregulated the expression of IL-1β, IL-6, IL-18, and pyrin domain-containing protein 3 (NLRP3) inflammasome, whereas knockdown GPR120 showed the opposite effect." (PMID 35624482, 2022). "Moreover, supplementation of BDNF attenuates astrocytosis and IL-1β expression after status epilepticus." (PMID 21949812, 2011). "The mean IL-1β level in afebrile status epilepticus attacks in intractable epilepsy patients was at a 11.7-fold increase higher than that of the afebrile controls (23.4 vs. 2.0 pg/mL) and a 7.5-fold increase higher than of fever only controls (23.4 vs. 3.1 pg/mL, p < 0.05)." (PMID 21989210, 2011). "In animal models of prolonged febrile seizures, IL-1β was significantly high in the hippocampus for over 24 hours and was elevated chronically only in rats developing spontaneous limbic seizures after febrile status epilepticus." (PMID 21989210, 2011). "However, the upregulation of pro-inflammatory markers, in particular IL-1β, antagonistic suppressors of cytokine signaling and eicosanoids after ihKA-induced status epilepticus lasted for several hours and up to 7 days after ihKA but reached basal levels in the chronic stage." (PMID 37874479, 2024). "In this study, we investigated the gene expression of proinflammatory cytokines IL-1β (Il1b) and IL-6 (Il6), and anti-inflammatory fractalkine (Cx3cl1) in the hippocampus, entorhinal cortex, and neocortex of rats at different time points after lithium-pilocarpine status epilepticus (SE)." (PMID 37047481, 2023). "In an animal model, pretreatment of silibinin (50, 100, and 200 mg/kg) in kainic acid (KA) - induced status epilepticus (SE) in mice showed a significant neuroprotective effect that might be due to reducing the expression of inflammatory cytokines IL-1β and TNF-α." (PMID 38106632, 2023). "Repeated application of levetiracetam (orally, 360 mg/kg for 2 days) attenuated the expression of interleukin-1β (IL-1β) and TNF-α in the hippocampus of mice after status epilepticus." (PMID 40431461, 2025). "Results obtained in experimental animal models and human patients have indicated that after status epilepticus, the chemokine CCL2-CCR2 signal induces neuronal cell death through the activation of STAT3 and the production of IL-1β." (PMID 34511129, 2021). "Both microglial pro-inflammatory cytokines (IL-1β and TNF-α) and anti-inflammatory cytokines (IL-4 and IL-10) showed increased expression after pilocarpine-induced status epilepticus, indicating a complex role of microglia in the epileptic brain." (PMID 34924959, 2021). "IL-1β and NLRP3 levels increased after amygdala kindling-induced status epilepticus, and inhibition of NLRP3 provided neuroprotection in rats following status epilepticus." (PMID 28109197, 2017).
status epilepticus (continued). "IL-1β-treated MSC-EXOs could prevent astrocytes and status epilepticus mice from experiencing LPS-induced inflammatory reactions, and its effects are mostly facilitated by the Nrf-2 signaling cascade." (PMID 39429946, 2024). "Pre-treatment with Tualang honey reduced neuroinflammation by reducing the elevation of TNF-α, IL-1β, glial fibrillary acidic protein, allograft inflammatory factor 1 and COX-2 in the cerebral cortex, cerebellum and brainstem of kainic acid-induced status epilepticus rat." (PMID 33435215, 2021). "Inhibiting this receptor during status epilepticus reduced tumor necrosis factor alpha (TNF-α), a major inflammatory cytokine, which, along with interleukin 1 beta (IL-1β), initiates the immune response in the CNS, leading to neuronal damage and hyperexcitability." (PMID 31935804, 2020). "In addition, an adolescent female with a diagnosis of refractory epilepsy was treated with anakinra first and then with canakinumab, an IL-1β antibody, during a nonconvulsive status epilepticus, which resulted in complete resolution of clinical seizures." (PMID 35837232, 2022). "Additionally, IL-1β increased calcium influx into neurons through NMDA receptors, promoting hyperexcitability in both in vitro and in vivo studies; meanwhile, Anakinra (recombinant IL-1Ra) controlled seizures in refractory epilepsy and a rodent model of status epilepticus." (PMID 40966229, 2025).